HTT (huntingtin)
Diseases named in the same sentence as HTT in open-access papers (continued):
Sharing a sentence is not in itself a finding about the gene and the disease.
Huntington disease (continued). "The most studied amyloid proteins are Aβ and tau in Alzheimer`s disease (AD), α-synuclein in Parkinson`s disease (PD), superoxide dismutase 1 (SOD1) in amyotrophic lateral sclerosis (ALS), and polyglutamine-rich huntingtin fragments in Huntington`s disease (HD)." (PMID 23340381, 2013). "In addition, cytoplasmic accumulation of proteins often implicates various neurodegenerative disorders, including the accumulation of rhodopsin in retinitis pigmentosa and the accumulation of polyQ-expanded huntingtin in Huntington's disease." (PMID 23754968, 2013). "14-3-3 ζ might scavenge misfolded Huntingtin proteins by facilitating the formation of aggregates possibly for neuroprotection; these aggregates are referred to as IBs in Huntington's disease." (PMID 24364034, 2013). "The notion that huntingtin protein may damage neurons by directly interfering with mitochondrial function in Huntington's disease, allows us to suggest that such a similar chain of events may occur in HF." (PMID 24303125, 2013). "Huntington's disease (HD) is characterized by a progressive course of disease until death 15–20 years after the first symptoms occur and is caused by a mutation with expanded CAG repeats in the huntingtin (htt) protein." (PMID 23956761, 2013). "There are also experimental evidences suggesting that certain intrinsically disordered proteins might in fact propagate like prions, including α-synuclein, the Aβ peptide and huntingtin, involved in Parkinson, Alzheimer and Huntington diseases, respectively." (PMID 23663289, 2013). "The same study found changes in the phosphorylation status of huntingtin (HTT), which acts as a transcription factor and a regulator of BDNF vesicle transport in physiological conditions, and when mutated, is responsible for Huntington’s disease." (PMID 24260418, 2013). "For example, we recently reported that targeting ATF4 does not have any consequences on mutant huntingtin aggregation in Huntingtońs disease, whereas ATF4 deficiency significantly reduces motor recovery after spinal cord injury." (PMID 23874395, 2013). "Huntington disease (HD) is a progressive neurodegenerative disorder, caused by an expanded CAG repeat within HTT gene encoding an abnormal long polyglutamine (polyQ) stretch in the huntingtin protein (Htt)." (PMID 24330808, 2013). "HTT is of particular interest in neurodegeneration because it is prone to polyglutamine expansion, the degree of which correlates to the severity of the development of Huntington’s disease, a devastating neurodegenerative disease." (PMID 23409969, 2013). "A key feature in Huntington disease (HD) is the accumulation of mutant Huntingtin (HTT) protein, which may be regulated by posttranslational modifications." (PMID 23871671, 2013). "Huntington's disease (HD) is a fatal, dominantly inherited neurodegenerative disease, which is caused by the expansion of a CAG repeat within exon 1 of the HTT gene, resulting in an extended glutamine tract in the huntingtin protein (HTT)." (PMID 24204323, 2013). "Here, we discuss how the proteasome is involved in the various stages of polyglutamine aggregation in Huntington's disease, and how alterations in activity may improve clearance of mutant huntingtin fragments." (PMID 23050151, 2012). "Huntington disease (HD) is an autosomal dominant neurodegenerative disorder resulting from an unstable expansion of a cytosine-adenine-guanine (CAG) trinucleotide repeat in the Huntingtin gene." (PMID 22359536, 2012). "Similarly, GluN2B containing receptors are selectively potentiated by mutant huntingtin, suggesting abnormal GluN2B subunit activity in Huntington's Disease." (PMID 22536151, 2012). "Huntington's disease (HD) is a dominantly-inherited, invariably fatal, familial neurodegenerative disease caused by an expansion in the polyglutamine encoding CAG tract in the huntingtin gene (Htt)." (PMID 23209424, 2012).
Huntington disease (continued). "No disease modifying treatment currently exists for Huntington's disease (HD), a fatal neurodegenerative disorder characterized by the formation of amyloid-like aggregates of the mutated huntingtin protein." (PMID 22475209, 2012). "Huntington disease (HD), a dominantly inherited neurodegenerative disorder, is caused by an abnormal CAG expansion within the first exon of the Huntingtin gene (HTT), leading to an expanded polyglutamine (polyQ) track in the HTT protein." (PMID 22383888, 2012). "N-terminal fragments of mutant huntingtin (htt) that terminate between residues 90–115, termed cleavage product A or 1 (cp-A/1), form intracellular and intranuclear inclusion bodies in the brains of patients with Huntington's disease (HD)." (PMID 23236391, 2012). "Onset of Huntington's disease is attributed to the presence of a high number of CAG trinucleotide repeat lengths within the Huntingtin (HTT) gene; in particular, when the number of CAG repeats exceeds 37, onset of Huntington's disease symptoms was much more likely to occur." (PMID 22151998, 2011). "Either way, our updated network analysis provides strong evidence for a link between DISC1 and HTT, and thus implies a degree of biological commonality between the neurological disorders of Huntington's disease and of schizophrenia and related major psychiatric illness." (PMID 21298101, 2011). "We applied the assay in a large-scale RNAi screening experiment with siRNA pools targeting the human kinome in HEK293 cells expressing wild type and mutant Huntingtin protein and we identified a number of synthetic lethal genetic interactions relevant to Huntington's disease." (PMID 22162763, 2011). "Similarly, in Parkinson's disease research, proteolytic reduction of aggregation-prone and neurotoxic mutant huntingtin is important in Huntington's disease research." (PMID 21631942, 2011). "We initially demonstrated that upregulation of autophagy, using the mTOR inhibitor rapamycin or its water-soluble ester CCI-779, reduced levels of soluble and aggregated mutant huntingtin and was protective in cell, Drosophila and mouse models of Huntington's disease." (PMID 21087849, 2011). "Moreover, deletion of the huntingtin polyglutamine tract in a huntington's disease mouse model with mutant huntingtin showed enhanced longevity that was most likely related to the activation of autophagy." (PMID 21858089, 2011). "Huntingtin is a large HEAT repeat protein first identified in humans, where a polyglutamine tract expansion near the amino terminus causes a gain-of-function mechanism that leads to selective neuronal loss in Huntington's disease (HD)." (PMID 21552328, 2011). "Huntington's disease (HD) is a genetically determined neurodegenerative disorder, the onset of which is known to depend upon the length of glutamine-encoding CAG-repeat sequences lying within the Huntingtin (HTT) gene." (PMID 21170307, 2010). "A means for measuring levels of soluble huntingtin proteins in clinical samples is essential for assessing the biological effects of potential mutant huntingtin (mtHtt) modifying treatments being developed for Huntington’s disease (HD)." (PMID 21278900, 2010). "Interestingly, daily administration of the A2A receptor agonist, CGS 21680, delays progressive deterioration of motor performance, huntingtin aggregation and increase in striatal choline levels in a transgenic mouse model (R6/2) of Huntington’s disease." (PMID 20190960, 2009). "The human protein huntingtin is involved in Huntington's disease." (PMID 19282972, 2009). "Proteolysis of huntingtin (Htt) plays a key role in the pathogenesis of Huntington's disease (HD)." (PMID 19488402, 2009). "Huntington's disease (HD) is an autosomal dominant, late-onset neurodegenerative disorder caused by a CAG repeat expansion in exon 1 of the HD gene which translates into a polyglutamine (polyQ) tract in the huntingtin (Htt) protein." (PMID 18954449, 2008).
Huntington disease (continued). "Molecular chaperones and their functions in protein folding have been implicated in several neurodegenerative conditions, including Parkinson's and Huntington's diseases, which are characterized by accumulation of protein aggregates (e.g. α-synuclein and huntingtin, respectively)." (PMID 16120223, 2005). "Thus, only inhibitors that can specifically modulate HTT acetylation may effectively slow the progression of Huntington’s disease and protect neuronal cells." (PMID 41303392, 2025). "Huntington’s disease (HD), similar to some other neurodegenerative disorders, results from a repeat expansion mutation, specifically a CAG trinucleotide repeat that encodes a polyglutamine (polyQ) sequence of 36 or more units within the Huntingtin (HTT) protein." (PMID 39722550, 2025). "Spinocerebellar ataxia type 1 (SCA1), spinocerebellar ataxia type 2 (SCA2) and Huntington disease are autosomal-dominant genetically determined neurodegenerative diseases, caused by the expanded CAG repeats (polyglutamine, polyQ) at the ATXN1, ATXN2 and HTT genes, respectively." (PMID 39974178, 2025). "Moreover, immunoprecipitation of HTT1a with the 1B12 and 11G2 antibodies from lysates of human as well as mouse Huntington’s disease brain was unsuccessful using assay conditions that pull down and enrich for full-length HTT with an anti-HTT N-terminal antibody." (PMID 40926977, 2025). "Huntington’s disease (HD) is an inherited neurodegenerative disorder characterized by an autosomal dominant mutation involving an abnormal expansion of CAG trinucleotide repeats in the huntingtin (HTT) gene, resulting in an expanded polyglutamine tract in the HTT protein." (PMID 40126262, 2025). "Huntington’s disease, often known as “Westphal disease,” is an autosomal dominant condition that causes the cytosine-adenine-guanine (CAG) trinucleotide to proliferate, resulting in the creation of a mutant protein known as Huntingtin (Htt), which causes the loss of psychomotor skills." (PMID 37492081, 2023). "For instance, PBN was shown to have a protective effect in a Huntington’s disease (HD) model, a progressive and autosomal dominant neurodegenerative disorder caused by an expanded CAG repeat in the huntingtin gene which encodes an abnormally long polyglutamine repeat in the huntingtin protein." (PMID 37371611, 2023). "Huntington’s disease (HD) is an autosomal dominant neurodegenerative disease characterized by progressive motor, cognitive, and behavioral symptoms The expansion of glutamine (CAG) repeats in the coding region of the Huntingtin gene leads to the mutated protein." (PMID 36902788, 2023). "Interestingly, a significant number (40%) of the identified RBM5 interactors also constitute known HTT interactors 79,80, with the shared interactors between RBM5 and HTT highly enriched for proteins involved in mRNA metabolic processes, neuron specific processes and Huntington’s disease." (PMID 37468457, 2023). "Huntington’s disease is an autosomal dominant neurodegenerative disorder that is caused by an excessive expansion of a CAG trinucleotide repeat, leading to the formation of polyglutamine-expanded mutant huntingtin (mHTT) protein aggregates which accumulate and eventually lead to cell death." (PMID 37627229, 2023). "Wild‐type uromodulin may also play a role, analogous to other dominant, gain‐of‐toxic function disorders such as Huntington disease, where the lack of wild‐type huntingtin causes a more severe phenotype." (PMID 37885358, 2023). "In Huntington’s disease, our group reported early shape changes detectable in MRI44 that have yet to be linked to precise patterns of inclusion bodies and accumulation of mutant huntingtin protein, as might be observed in histological stains." (PMID 37284027, 2022).
Huntington disease (continued). "Finally, using a well-established Drosophila melanogaster model for Huntington’s disease (Q128HD-FL), which expresses the mutated form of human huntingtin, the neuronal function improved after MS3 treatment, definitively proving the in vivo efficacy of this aptamer." (PMID 35563194, 2022). "A recent study of Huntington’s disease suggested that age-related signatures were different between iPSC-derived neurons and directly converted neurons; therefore, pathogenic huntingtin aggregates were detected only in converted neurons but not in iPSC-derived neurons." (PMID 35641224, 2022). "Thus, mutant Huntingtin could lead to defective neurogenesis during embryonic development leading to Huntington's disease later in life." (PMID 35832065, 2022). "As several therapies aimed at lowering mutant huntingtin (mHTT) brain levels in Huntington’s disease (HD) are currently being investigated, noninvasive positron emission tomography (PET) imaging of mHTT could be utilized to directly evaluate therapeutic efficacy and monitor disease progression." (PMID 34651228, 2022). "Huntington disease (HD) is the most frequent monogenetic neurodegenerative disease and can be unequivocally diagnosed even in the preclinical stage, at least in all individuals in whom the CAG expansion mutation in the huntingtin gene (HTT) is in the range of full penetrance." (PMID 34762178, 2022). "In this manner, yeast models of Alzheimer’s disease (AD), Parkinson’s disease (PD) and Huntington disease (HD) have been developed, in which respective aggregating proteins, amyloid β, α-synuclein and huntingtin, are produced." (PMID 35563497, 2022). "However, due to the ubiquitous presence of huntingtin, astrocytes are also dysfunctional, and neuroinflammation may additionally contribute to Huntington’s disease pathology." (PMID 35740453, 2022). "To date, mutant HTT mRNA has not been identified as an in vivo hallmark of Huntington’s disease." (PMID 36458209, 2022). "With an estimated prevalence of 1–15 cases per 100,000 inhabitants, Huntington’s disease (HD) (OMIM #143100) is a monogenic neurodegenerative disorder that similarly affects both sexes and is caused by an abnormal expansion of CAG repeats in the first exon of the Huntingtin (HTT) gene." (PMID 35628221, 2022). "Huntington’s disease (HD) is an autosomal dominant, progressive neurodegenerative disorder caused by a CAG trinucleotide repeat expansion in the first exon of the HTT gene encoding huntingtin (HTT), a ubiquitously expressed protein involved in transcriptional regulation." (PMID 36362235, 2022). "Huntington disease (HD) is a rare but fatal autosomal dominant neurodegenerative disease caused by a repeat CAG expansion, encoding polyglutamine (polyQ) stretch in the huntingtin (Htt) gene, resulting in motor and cognitive deficits that are progressively disabling." (PMID 35082783, 2021). "Although the exact pathophysiology underlying Huntington’s disease is not known, aggregates of mutant huntingtin, which form inclusion bodies, may disrupt neuronal homeostasis and, in this way, disrupt function of both the brain and cochlea." (PMID 34539328, 2021). "Huntingtin protein (HTT) is post-translationally myristoylated following the cleavage by caspases, and disruption of this myristoylation process on HTT fragment might be involved in the pathophysiology of Huntington disease." (PMID 34395449, 2021). "The brains of patients with Huntington's disease exhibit evidence of alterations in methylation status or acetylation status and inhibition of a histone deacetylase may prevent the development of cognitive deficits as well as huntingtin expansion." (PMID 32194572, 2020). "Similar to AD, during HD, aggregation of insoluble huntingtin protein aggregates has been observed in different experimental models as well as in brain tissues from patients with Huntington disease." (PMID 31941036, 2020).
Huntington disease (continued). "Huntington's disease (HD), also known as Huntington's chorea, is a hereditary, autosomal, and dominant neurodegenerative disease; the disease is caused by a dominantly inherited cytosine-adenine-guanine (CAG) trinucleotide repeat expansion in the huntingtin gene, on chromosome IV." (PMID 32963705, 2020). "In Huntington's disease (HD) in vivo models, a number of genetic and pharmacological mechanisms aimed to induce autophagy have been successfully tested, demonstrating the role of autophagy in promoting the elimination of mutant huntingtin (mHTT) aggregates and its neuroprotective effect." (PMID 32098205, 2020). "A key aim of current therapies in development for Huntington's disease is to reduce mutant huntingtin in the nervous system, which has already been successfully used as a marker of target engagement for current trials of huntingtin-lowering therapies in manifest Huntington's disease." (PMID 32470422, 2020). "Huntington’s disease (HD) is an autosomal dominant, neurodegenerative disease caused by an expanded CAG repeat (≥40 repeats, full-penetrance) in the gene for the huntingtin protein (HTT), though symptoms may also occur in some with CAG repeat lengths ≥ 36 (reduced penetrance range)." (PMID 31910203, 2020). "In a model of Huntington’s disease, mitochondrial dysfunction was caused by the inhibition of PGC-1α by a mutant form of the huntingtin protein; overexpression of PGC-1α rescued cells from the deleterious effect of huntingtin, demonstrating the significance of PGC-1α." (PMID 31717375, 2019). "Additionally, injecting AAV9-miRNA targeting human huntingtin (HTT) in the striatum of transgenic Huntington’s disease (HD) sheep so that these express the full-length HTT gene reduced the mRNA and protein of human HTT by 50–80% in the striatum at 1 and 6 months postinjection." (PMID 31552084, 2019). "Since our data showed that i.p. injection of felodipine could reduce the levels of mutant huntingtin, the toxic causative agent in Huntington’s disease, we tested whether long-term treatment could ameliorate signs of disease in the B6HD Huntington’s disease mouse model." (PMID 31000720, 2019). "How huntingtin (HTT) triggers neurotoxicity in Huntington’s disease (HD) remains unclear." (PMID 30994454, 2019). "In addition, some pathological signals from Huntington’s disease might occur simultaneously in both the cardiovascular and nervous systems, since mutant huntingtin protein is expressed in both." (PMID 29875678, 2018). "Moreover, aggregates of huntingtin (Htt) exon 1 are known hallmarks of Huntington’s disease." (PMID 30065623, 2018). "Huntington’s disease (HD), which presents with a wide range of neurological, psychiatric and other symptoms, is one of the most common and is caused by a tandem repeat (CAG) expansion leading to an expanded polyglutamine tract in the disease protein (huntingtin)." (PMID 29945620, 2018). "Huntington's disease (HD) is a progressive and autosomal dominant neurodegeneration caused by CAG expansion in the huntingtin gene (HTT), but the pathophysiological mechanism of mutant HTT (mHTT) remains unclear." (PMID 28611571, 2017). "Huntington disease (HD) is a neurodegenerative disorder resulting from a trinucleotide repeat expansion in the huntingtin gene." (PMID 29196686, 2017). "Importantly, HTT, whose expression is abrogated by the pQ expansion in Huntington’s disease, was recently found to facilitate selective autophagy by acting as a scaffold between autophagy adaptor p62/SQSTM1 and core autophagy molecules such as Atg1/ULK1 and Atg8/LC3 proteins." (PMID 28737703, 2017). "Huntington’s disease (HD) is an autosomal dominant disorder, typically characterized by chorea due to a trinucleotide repeat expansion in the HTT gene, although the clinical manifestations of patients with juvenile HD (JHD) are atypical." (PMID 28789621, 2017).